PBRM1 (polybromo 1)
Diseases named in the same sentence as PBRM1 in open-access papers (continued):
Sharing a sentence is not in itself a finding about the gene and the disease.
chordoma (14 papers, 2017 to 2025). Chordomas are rare malignant tumors arising from embryonic remnants of the notochord in axial skeleton. "It appears that a subset (20.3%) of chordoma is enriched with at least one SWI/SNF complex mutation: PBRM1, ARID1A, or SETD2." (PMID 39941902, 2025). "The first demonstration of a high antitumor activity of tazemetostat in a PDX model harboring a PBRM1 variant supports further evaluation for EZH2-inhibitors in this subgroup of chordomas." (PMID 35326637, 2022). "Mutations in subunits of SWI/SNF complexes, including the PBRM1 gene, have frequently been reported in chordomas as cancer driver genes." (PMID 35326637, 2022). "This particular chordoma did not express PD-L1 before treatment but did contain a loss-of-function mutation in PBRM1, which again hints at a role for the chromatin-remodeling complex in response to PD-1 blockade in chordomas." (PMID 34440251, 2021). "Recently, other components of SWI/SNF complex have also been implicated in chordoma pathogenesis, such as PBRM1 as a potential driver gene for chordoma." (PMID 34070849, 2021). "We administrated pembrolizumab (200 mg) every 3 weeks to a metastatic chordoma patient that was found to harbor A1209fs mutation of the PBRM1 gene." (PMID 33392069, 2020). "Additionally, similar to other reports, mutations in PBRM1 are found mostly in the chordoma NOS or conventional subtype." (PMID 39941902, 2025). "Interestingly, chordoma mutations in the PBRM1, ARID1A, or SETD2 genes are frequently missense mutations." (PMID 39941902, 2025). "Like chordoma, chromosome 3p loss and PBRM1 mutations are very common in sporadic ccRCCs32,33." (PMID 33536423, 2021). "Mutations of the PBRM1 gene may represent a new target of immunotherapies in chordoma and hence the need for further exploration." (PMID 33392069, 2020). "In PBRM1, the recurrence of the missense mutation D1055Y (n = 2) and the nonsense mutation W1417* (n = 2) in samples suggest these particular variants may be biologically significant in chordoma." (PMID 39941902, 2025). "Interestingly, in the CD39 PDX model and the corresponding primary patient’s tumor, we observed different variants affecting the PBRM1 gene, therefore suggesting the primordial role for PBRM1 mutations as driver events in chordoma oncogenesis, already reported." (PMID 35326637, 2022). "PBRM1 mutations were present in 8.3% (n = 9/116) of chordoma NOS cases and 7.1% (n = 1/14) of conventional chordoma, while ARID1A mutations appeared in 6.4% (n = 7/116) of chordoma NOS cases and 14.3% (n = 2/14) of conventional chordoma." (PMID 39941902, 2025). "In contrast, adult chordoma more commonly displays PBRM1 alterations and homozygous deletions of the CDKN2A/2B locus, reflecting the findings in this study." (PMID 39941902, 2025). "These mutations affect various subunits of the SWI/SNF chromatin remodeling complex, with ARID1A being the most frequently mutated gene, followed by SMARCA4, ARID1B, ARID2, PBRM1, and SMARCB1, mutations we have found to be common in adult chordoma." (PMID 39941902, 2025). "As found in the prior genomic analysis of sporadic chordoma, PBRM1 was identified as a significant tumor suppressor gene in tumorigenesis." (PMID 38892063, 2024). "From our chordoma xenograft panel, we selected three models, two of them harboring a homozygous deletion of CDKN2A/2B genes, and the last one a PBRM1 pathogenic variant (as control)." (PMID 36505864, 2022). "Mutations affecting PBRM1, a specific subunit of the PBAF complex, seem to be potential driver events for chordomas." (PMID 35326637, 2022). "In one PBRM1-mutated model, we demonstrated a strong therapeutic efficacy of the EZH2-inhibitor tazemetostat, encouraging further research on EZH2-inhibitors in chordomas." (PMID 35326637, 2022).
chordoma (continued). "Here, the authors carry out whole genome sequencing of 80 skull base chordoma tumours and identify the SWI/SNF component—PBRM1—as a frequently mutated gene." (PMID 33536423, 2021). "Mutations in three other SWI/SNF members—PBRM1, SETD2, ARID1A—have been identified as potential drivers in chordomas; however, the relevance of these mutations to chordoma etiology remains to be elucidated." (PMID 32733369, 2020). "Our findings of enrichments in SWI/SNF complex mutations, such as PBRM1, ARID1A, SETD2, and SMARCA2, indicate that epigenetic therapies may be effective in some chordoma cases." (PMID 39941902, 2025). "Mutations in PBRM1, ARID1A, and SETD2 appear to be enriched in chordoma." (PMID 39941902, 2025). "Additionally, mutations within the chromatin remodeling genes PBRM1, SETD2, and SMARCB1, which have previously been recognized as frequently altered in chordoma, were each identified in two patients." (PMID 39135136, 2024). "Although an efficient antitumoral activity of the anti-EZH2 tazemetostat has already been reported in one SMARCB1/INI1 negative chordoma, there are no data concerning anti-EZH2 drugs on PBRM1-mutated chordoma, which is one of the most common genetic type." (PMID 35326637, 2022). "Genetic features of chordomas include chromosomal copy number loss of the tumor suppressor gene CDKN2A as well as structural variants in genes that encode members of the chromatin-remodeling complex, including PBRM1 and SMARCB1." (PMID 34440251, 2021). "Here, we report a case of a chordoma patient who was negative for PD-L1 expression in the original tumor and found to possess the A1209fs mutation of the PBRM1 gene." (PMID 33392069, 2020). "In a case report, a patient with chordoma receives pembrolizumab and achieves a PFS of 9.3 months by targeting PD-1 receptors of lymphocytes, but the immunotherapy benefit may be related to the A1209fs mutation of the PBRM1 gene." (PMID 36520826, 2022). "Some chordomas also exhibit alterations in genes related to chromatin remodeling, such as ARID1A and PBRM1." (PMID 39941902, 2025). "Chordomas commonly activate pathways such as EGFR, PDGFβ, IGFR1, IGF1, mTOR, MET, and PI3K and involve chromatin remodeling genes such as ARID1A, PBRM1, and SETD2." (PMID 39193055, 2024). "Moreover, we established for the first time a strong antitumor effect of the EZH2-inhibitor tazemetostat in a PBRM1-mutated PDX, suggesting PBRM1 as a new potential theragnostic marker in chordoma and supporting further evaluation of EZH2-inhibitors in this subgroup of chordomas." (PMID 35326637, 2022). "In contrast, the other nine pediatric chordoma patients (diagnosed ≤ 20 years) appeared to have quiet genomes, characterized by low mutational burden and the absence of driver events (alterations in PBRM1, CDKN2A/B, TBXT genes), compared with adult chordoma patients." (PMID 33536423, 2021). "We first examined the two potential driver events, PBRM1 and CDKN2A/B status, in relation to chordoma-specific survival (CSS) and recurrence-free survival (RFS)." (PMID 33536423, 2021). "In summary, we identified candidate driver events (PBRM1+, SETD2+, CDKN2A/B+, TBXT/LYST+) in 33.75% (27 out of 80) of the skull-base chordoma patients we sequenced." (PMID 33536423, 2021). "Consistent with findings from previous studies of sacral chordoma, we found that alterations of PBRM1 and CDKN2A/2B locus were the most common events in chordoma." (PMID 33536423, 2021). "Drivers in another SWI/SNF gene, PBRM1 (10/104 cases) and the histone methyltransferase, SETD2 (5/104) implicate defective chromatin modelling as a major driver of chordoma." (PMID 29026114, 2017). "In this cohort, composed of 116 patients with chordoma NOS, 14 with conventional chordoma, and 3 with dedifferentiated chordoma, mutations in SWI/SNF complex genes (PBRM1, ARID1A, SETD2) were not significantly enriched or depleted across subtypes (p > 0.05)." (PMID 39941902, 2025).
chordoma (continued). "Given the role of PBRM1 and SETD2 in chromatin remodeling, our data suggest that epigenetic dysregulation may play an important role in chordoma development." (PMID 33536423, 2021). "Here we conduct whole genome sequencing of 80 skull-base chordomas and identify PBRM1, a SWI/SNF (SWItch/Sucrose Non-Fermentable) complex subunit gene, as a significantly mutated driver gene." (PMID 33536423, 2021). "Associations for PBRM1 alterations and 22q deletion for both CSS and RFS remain significant when we restricted the analyses to the 53 patients who were not previously diagnosed with or treated for chordoma and who did not have presurgery RT." (PMID 33536423, 2021). "Notably, recurrent mutations in SETD2 (e.g., T2338Hfs31 in exon regions, n = 2) and PBRM1 (e.g., D1055Y, n = 2; W1417, n = 2) were absent from the COSMIC database’s chordoma entries, indicating potential novel hotspots." (PMID 39941902, 2025).
lung cancer (14 papers, 2017 to 2025). A malignant neoplasm involving the lung. "CRISPR screens proved that mutations of Polybromo-1 (PBRM1) gene attenuate the effects of EGFR inhibitors in lung cancer by enhancing the continuity of AKT signaling." (PMID 39696697, 2024). "In vivo, once weekly administration of PRT2527 (30 mg/kg) potently inhibited tumor growth in a H1703 (PBRM1-protein-deficient lung cancer) CDX model (39% TGI)." (PMID 38371625, 2024). "H1703 is a lung cancer cell line with PBRM1 protein loss that has been extensively used to characterize responses to Sunitinib in monotherapy and in combination with various agents." (PMID 38371625, 2024). "But to our knowledge, the frequency and clinical relevance of PBRM1 mutation in lung cancer remain unknown." (PMID 32195359, 2020). "Furthermore, in lung cancer, the crosstalk between polybromo 1 (PBRM1) and YTHDF2 was required for the effective synthesis of HIF-1 protein." (PMID 36291060, 2022). "However, lung cancer patients with mutant PBRM1 benefit less from treatment-related survival." (PMID 33633793, 2021). "To confirm this hypothesis, we analysed the role of PBRM1 in the cells that have impaired BRG1, A549 and H1299 lung cancer cells." (PMID 34200988, 2021). "In addition, SETD2 is mutated in other cancer types, such as non‐small cell lung cancer, where VHL and PBRM1 mutations rarely occur, although this does not preclude the possibility that SETD2 cooperates with other mutated genes such as K‐RAS in context of lung cancer." (PMID 37418588, 2024).
cholangiocarcinoma (11 papers, 2014 to 2026). A carcinoma that arises from the intrahepatic biliary tree (intrahepatic cholangiocarcinoma) or from the junction, or adjacent to the junction, of the right and left hepatic ducts (hilar cholangiocarcinoma). "When combined with KrasG12D mutation, Pbrm1 KO/KrasG12D mice had shorter survival and were more likely to develop cholangiocarcinomas, whereas Pbrm1 wild type/KrasG12D mice predominantly developed hepatocellular neoplasms." (PMID 41513002, 2026). "Using The Cancer Genome Atlas (TCGA) database, a waterfall plot analysis revealed that PBRM1 is the most frequently mutated gene in cholangiocarcinoma." (PMID 39823528, 2025). "In this study, we initially examined the mutations linked to cholangiocarcinoma using the TCGA dataset and identified PBRM1 mutation frequency at 20%, making it the most commonly mutated gene in iCCA." (PMID 39823528, 2025). "Meanwhile mutation in one of ARID1A and PBRM1 were found in almost half of 32 intrahepatic cholangiocarcinomas through exomic sequencing." (PMID 35672673, 2022). "Whether in high- and low- risk, the frequent alterations in ARID1A and PBRM1 in cholangiocarcinomas highlight the key role of chromatin remodeling which in cholangiocarcinomas." (PMID 35672673, 2022). "We have successfully developed a reliable gene therapy nanomedicine for in vivo cholangiocarcinoma treatment through modulating PBRM1 expression." (PMID 39823528, 2025). "Additionally, a reliable gene therapy nanomedicine has been developed for in vivo cholangiocarcinoma treatment through the modulation of PBRM1 expression." (PMID 39823528, 2025). "Notably, we observed that PBRM1 mutations showed a unique pattern in KIRC and cholangiocarcinoma (CHOL)." (PMID 30760718, 2019). "Alterations in chromatin remodeling genes (ARID1A, BAP1, IDH1, IDH2, PBRM1, SMARCB1) were found in 30.7% (47/153) of cancers in our series, confirming recent reports on the significant involvement of these genes in cholangiocarcinoma." (PMID 24867389, 2014). "Our in vivo experiments validated that nanomedicines can precisely modulate PBRM1 expression in cholangiocarcinoma lesions, thereby exerting negative control over subcutaneous tumor growth." (PMID 39823528, 2025).
intrahepatic cholangiocarcinoma (9 papers, 2016 to 2026). A carcinoma that arises from the intrahepatic bile duct epithelium in any site of the intrahepatic biliary tree. "PBRM1, a key subunit of this complex, is frequently mutated in intrahepatic cholangiocarcinoma (iCCA)." (PMID 41513002, 2026). "The last group was enriched for individuals with a diagnosis of perihilar cholangiocarcinoma (PHCC) and GBC (n = 38; 79.2%), whereas patients with intrahepatic cholangiocarcinoma (ICC) were more likely to harbor IDH1-2/BAP1/PBRM1 mutations (n = 14; 60.9%)." (PMID 33297469, 2020). "Polybromo‐1 (PBRM1) serves as a crucial regulator of gene transcription in various tumors, including intrahepatic cholangiocarcinoma (iCCA)." (PMID 39823528, 2025). "This research demonstrates that PBRM1 has the capability to inhibit the progression of intrahepatic cholangiocarcinoma (iCCA)." (PMID 39823528, 2025). "Isocitrate dehydrogenase 1/2 (IDH1/2), BAP1, ARID1A and PBRM1 have been reported as the most frequent mutant genes in intrahepatic cholangiocarcinoma (ICC), and their relationships with clinicopathological features and prognosis were researched in this study." (PMID 32293336, 2020).
non-small cell lung carcinoma (8 papers, 2020 to 2025). A group of at least three distinct histological types of lung cancer, including non-small cell squamous cell carcinoma, adenocarcinoma, and large cell carcinoma. "In contrast, in a retrospective analysis conducted at three Chinese institutions, presumably in Asian patients, PBRM1 mutations were infrequent in patients with non-small cell lung cancer (84/2,767, 3%)." (PMID 41199851, 2025). "The PBRM1 gene is crucial in suppressing non-small cell lung cancer (NSCLC) tumor function, and its loss may lead to renal cell carcinoma tumor growth." (PMID 38637684, 2024). "In the three cancer types with the most POL&PBRM1 patients (colorectal cancer, endometrial cancer, and non-small cell lung cancer), the POL&PBRM1 group also had the highest TMB among the four groups." (PMID 39218995, 2024). "When univariately examining LOF mutations in PBRM1 and ARID2 as well as LOF in PBRM1 alone, they remained significantly associated with adverse OS in non-small-cell lung cancer." (PMID 32820162, 2020). "In individual cancer types, PBRM1 was correlated with worse OS in non-small-cell lung cancers (n = 983; HR 2.91, p < 0.001) after adjusting for TMB and total CNA." (PMID 32820162, 2020). "Given the higher frequency of ARID2 mutations in the non-RCC cohorts, we combined PBRM1 and ARID2 LOF and non-LOF mutations for individual subtype analysis, which was significant in non-small-cell lung cancers." (PMID 32820162, 2020). "In our non-small cell lung cancer cohort, PFS, objective response rate and disease control rate had obvious superiority in the patients with PBRM1 mutation than those without PBRM1 mutation (PFS: HR = .268, 95% CI: 084–.854, p = .04, ORR: 55.56% vs. 20.00%, p = .027, DCR: 100% vs. 75.20%)." (PMID 36699446, 2022).
gastric cancer (7 papers, 2016 to 2025). A primary or metastatic malignant neoplasm involving the stomach. "DNA whole-exome sequencing was performed on 7 cases of gastric cancer with loss of PBRM1 expression." (PMID 35928964, 2022). "Interestingly, PBRM1 loss was associated with a decreased angiogenesis score in gastric cancer, and a similar trend was observed in endometrial and bladder cancers." (PMID 32358509, 2020). "To attempt to contextualize this previous work with our current findings, we analyzed the effects of PBRM1 loss in four additional TCGA datasets with sufficient sample size (microsatellite stable endometrial cancer, microsatellite instable endometrial cancer, gastric cancer, and bladder cancer)." (PMID 32358509, 2020). "The expression levels of EBV-miR-BART11-3p, EBV-miR-BART11-5p, EBV-miR-BART17-3p, FOXP1, PBRM1, and PD-L1 were determined using samples of NPC and EBV-associated gastric carcinoma tissues by performing IHC or ISH methods." (PMID 35165282, 2022). "In conclusion, PBRM1 gene abnormalities may play an important carcinogenic role in some gastric cancer subgroups and may affect their tumor immune activity, thereby influencing the clinicopathological and overall prognosis of GAC." (PMID 35928964, 2022). "FOXP1 and PBRM1 expression levels were low, while EBV-miR-BART11-3p, EBV-miR-BART11-5p, and EBV-miR-BART17-3p were highly expressed in NPC and gastric carcinoma tissues." (PMID 35165282, 2022).